IL4R (interleukin 4 receptor)
Diseases named in the same sentence as IL4R in open-access papers (continued):
Sharing a sentence is not in itself a finding about the gene and the disease.
IL4R also shares sentences with these, for which no sentence is quoted: Allergy (24 papers); chronic rhinosinusitis (5); depression (4); immunodeficiency (4); dermatitis (3); eosinophilic esophagitis (3); rhinitis (3); adenocarcinoma (2); airway allergy (2); bronchiectasis (2); childhood asthma (2); chronic rhinosinusitis with nasal polyps (2); colorectal adenoma (2); dementia (2); epilepsy (2); Hepatitis (2); liver disease (2); lung disease (2); mental disorder (2); polyp (2); prostate tumor (2); prurigo nodularis (2); schizophrenia (2); squamous cell carcinoma (2); actinic keratosis (1); acute lung injury (1); acute respiratory distress syndrome (1); age-related macular degeneration (1); alopecia areata (1); amyloid (1).
A further 67 diseases each share a sentence with IL4R in 1 paper.